IL13RA2 (interleukin 13 receptor subunit alpha 2)
Diseases named in the same sentence as IL13RA2 in open-access papers (continued):
Sharing a sentence is not in itself a finding about the gene and the disease.
glioblastoma (continued). "In addition, glioblastoma patients who received IL-13Rα2- and EGFRvIII-targeting CAR T cells showed clinical responses in early clinical studies." (PMID 33572835, 2021). "Given the significant expression of IL13Rα2 in other late-stage human tumors (ovarian, pancreatic, glioblastoma), we believe that 5.5.4 mAbs might be clinically useful for these other human tumors." (PMID 33917458, 2021). "For example, a bispecific CAR molecule directed against both IL13Rα2 and HER2 (TanCAR) has been shown to promote tumor regression and increase survival in mice xenografted with a HER2+ IL13Rα2+ human glioblastoma cell line compared to CAR T cells against either target alone." (PMID 34054867, 2021). "In several solid tumors, studies reported that IL13RA2 could predict poorer survival, such as glioblastoma 18, breast cancer 19, colorectal cancer 20 and pancreatic cancer." (PMID 31823484, 2020). "A few clinical trials have been reported applying IL13Rα2 CAR-T in glioblastoma treatment." (PMID 31979318, 2020). "For example, in glioblastoma multiforme 18, no significant change was observed in cell proliferation in IL13RA2 loss tumor cells with the absence of mutant EGFR (EGFRvIII)." (PMID 31823484, 2020). "Well-defined targets for glioblastoma are IL-13Rα2, HER2, EGFRvIII and EphA2." (PMID 30863720, 2019). "The tandem CAR was able to bind either HER2 or IL-13Rα2 and to lyse glioblastoma cells." (PMID 30736355, 2019). "Similarly, Brown and colleagues reported low persistence and limited anti-tumor activity of anti-IL13Rα2-CAR T cells with an unmodified IgG4-hinge in patients with glioblastoma." (PMID 31108883, 2019). "The strongest difference between normal and glioblastoma tissue was shown by IL13Rα2, which led to the hypothesis that IL13Rα2 is a particularly tumor-specific binding partner." (PMID 31561550, 2019). "These include humanized HER2 CARs that were shown to have a central memory phenotype in the context of treating breast cancer xenografts; IL13Rα2 CARs that showed proliferation and cytotoxicity in a mouse model of glioblastoma; and FAP CARs in IP mouse models of MPM." (PMID 30804938, 2019). "Hedge and colleagues designed a HER2/IL13Rα2 tandem CAR for the treatment of glioblastoma." (PMID 30467505, 2018). "Given our results with glioblastoma cells and the abundant expression of IL13Rα2 in other tumours, we can envisage that this strategy could be useful for targeting glioblastoma and, probably, other pathologies." (PMID 30318506, 2018). "In one reported case, autologous CAR T cells targeting IL13Rα2 induced a complete response in a patient with recurrent multifocal glioblastoma, with dramatic improvements in quality of life and a return to normal life activities, allowing 7,5 disease free months survival." (PMID 29337870, 2018). "Since AP-1 family members are upregulated in astrocytoma and glioblastoma samples also, it is possible that IL-13Rα2 and AP-1 pathway may play a role in invasion, migration and infiltration of glioblastoma tumors within the intracranial cavity." (PMID 30572904, 2018). "IL13RA2 is a tumor antigen-like factor, which is highly expressed in the glioblastoma patients." (PMID 27349736, 2016). "In fact, siRNA-mediated knockdown of IL13RA2 induced apoptosis in glioblastoma cells." (PMID 26114873, 2015). "It was reported that tumor apoptosis was induced by upregulation of IL13RA2 in glioblastoma cells." (PMID 26114873, 2015). "Silencing of IL13RA2 also promotes glioblastoma cell death by inducing apoptosis." (PMID 26114873, 2015). "Recent studies showed that targeting IL13RA2 may be a new therapy for glioblastoma and head and neck squamous cell carcinoma." (PMID 26114873, 2015). "Consistent with our findings, there is a growing list of cancers in which overexpression of IL13Rα2 has been reported to promote tumor progression, including glioblastoma, pancreatic, ovarian, and colon cancers, suggesting a critical role for this alteration in a multitude of cancers." (PMID 26208975, 2015).
glioblastoma (continued). "Silencing of IL13Rα2 prolonged mice survival in mouse glioblastoma xenograft models." (PMID 26418721, 2015). "Based on the many studies which reported induction of IL13Rα2 on a variety of cell types following cytokine stimulation, we envisioned that this strategy for IL13Rα2 induction may be conserved for glioblastoma as well." (PMID 24787244, 2014). "IL13RA2 is reportedly over expressed in ~90% of glioblastoma samples." (PMID 20423517, 2010). "Additionally, an ongoing phase I study investigating bivalent CAR (targeting EGFR and IL13Rα2) engineered T cells recently reported transient reductions of recurrent glioblastoma, which has median overall survival of less than a year, in all treated patients (n=6)." (PMID 40808942, 2025). "In addition, IL13Rα2-targeted CAR T cells are being worked on for glioblastoma." (PMID 39364321, 2024). "Other studies have examined HER2 and IL-13Ra2, both highly expressed in GBM tissues, targeting CAR T cells in glioblastoma with promising initial results." (PMID 38254796, 2024). "In this study, SEB was fused to interleukin-13 (IL13), which forms a complex with IL13 receptor α2 (IL13Rα2) overexpressed in glioblastoma multiforme (GBM) cells for therapeutic goals." (PMID 39118800, 2024). "However, killing of glioblastoma cells expressing lower levels of IL13Rα2 varied among the CAR-Ts." (PMID 37563127, 2023). "IL-13Rα2 is the most common therapeutic target in glioma; Recent studies have shown that IL-13Rα2 can signal through the AP-1 pathway where it cooperates with other molecules, such as chitinase 3-like 1 (CHI3L1) and epidermal growth factor receptor variant III (EGFRvIII), in glioblastoma." (PMID 37158824, 2023). "Since its discovery as an overexpressed protein in glioblastoma multiforme (GBM), IL-13Rα2 has become an attractive therapeutic target for cancer." (PMID 36830725, 2023). "Our group has developed and clinically translated an IL13(E12Y) ligand–based CAR targeting the cancer antigen IL13Rα2 for treatment of glioblastoma (GBM)." (PMID 36968221, 2023). "However, IL13Ra2 is overexpressed in 60% of glioblastoma tumors." (PMID 37443750, 2023). "Next, we investigated whether IL-13Rα2 could provide a growth advantage in the presence of wtEGFR, using a tetracycline (Tet)-inducible wtEGFR (denoted as U251-E6) or mutant EGFRvIII (denoted as U251-E18) in the glioblastoma cell line U251MG." (PMID 29203859, 2017). "This trispecific TCE was designed to address the tumor heterogeneity of glioblastoma and demonstrated efficient tumor growth control in a GBM model with heterogenous expression of IL13Rα2 and EGFRvIII, resembling the complex tumor environment in human GBM." (PMID 40936895, 2025). "Xie’s group utilized glucose-coated ultra-small superparamagnetic iron oxide nanoparticles (USPIOs) to label anti-hEGFRvIII/IL13Rα2 CAR-T cells, enabling non-invasive MRI monitoring of their infiltration and persistence in glioblastoma." (PMID 40672956, 2025). "For example, in glioblastoma, a case study involving CAR-T cells targeting IL13Ra2 reported a decrease in IL13Ra2 expression in recurrent tumors." (PMID 40382583, 2025). "For glioblastoma, CAR-T therapies targeting IL13Rα2, EGFRvIII, and HER2 remain in early-phase (I/II) trials." (PMID 40386781, 2025). "Later, the third generation CAR-T cells targeting interleukin 13 receptor alpha 2 (IL13Rα2) and with a CD28 transmembrane domain were shown to be effective against glioblastoma in mouse xenograft models." (PMID 39996879, 2025). "This strategy has been explored in the preclinical models of solid tumors like glioblastoma (HER2 and IL13Rα2 CARs) and rhabdomyosarcoma (FGFR4 and B7-H3 CARs) and shown to result in superior durability of anti-tumor effects." (PMID 40808942, 2025). "The researchers administered intratumoral glucocorticoid receptor KO anti-IL13Rα2 CAR T cells plus systemic glucocorticoids and aldesleukin in six patients with progressive/recurrent grade III or IV glioblastoma." (PMID 41354926, 2025).
glioblastoma (continued). "Glioblastoma studies revealed that combining HER2 and IL13Ra2-targeted CARs resulted in improved anti-tumor activity and reduced antigen escape compared to other dual-targeting strategies." (PMID 40382583, 2025). "A study in its initial stage treated six patients with recurrent glioblastoma using CAR T cells that targeted EGFR and IL13Rα2 through intrathecal delivery (NCT05168423)." (PMID 40060757, 2025). "CAR-T cell therapy for glioblastoma (GBM) targets several antigens, including interleukin-13 receptor α2 (IL13Rα2), human epidermal growth factor receptor 2 (HER2), epidermal growth factor variant III (EGFRvIII), and erythropoietin-producing hepatocellular carcinoma A2 (EphA2)." (PMID 40092990, 2025). "Recent clinical trials with IL13Rα2-targeting CAR T-cells have shown promise, particularly in recurrent glioblastoma, demonstrating potential for tumor reduction in select cases." (PMID 39796773, 2025). "A study by Yin and co-workers showed that BiTE-secreting T cells EGFR and interleukin-13 receptor alpha 2 (IL13Rα2) exhibited superior antitumour activity with higher sensitivity and specificity compared to their CAR-T counterparts in glioblastoma model." (PMID 39450176, 2024). "For example, chimeric antigen receptor T cells simultaneously targeting HER2, IL13Rα2, and ephrin-A2 have been reported to overcome antigenic heterogeneity and lead to improved treatment outcomes in IDH wild-type glioblastoma." (PMID 37944044, 2024). "GAS treatment improved the mobility of IL-13Rα2 CAR T, enhancing their ability to recognize the tumor antigen of glioblastoma, indicating its potential application of CAR T for the treatment of solid tumors." (PMID 39835140, 2024). "Brown and his colleagues generated an off-the-shelf, steroid-resistant, IL13Rα2-targeted CAR-T and found it was safety and induced transient tumor reduction and/or tumor necrosis in patients with glioblastoma." (PMID 39555054, 2024). "To date, CAR-T cells targeting EGFRVIII, IL13Ra2 and HER2 have been applied in clinical studies of glioblastoma and have shown promising results in a few patients." (PMID 39877353, 2024). "Here we report a completed phase I trial evaluating IL-13Rα2-targeted CAR-T cells in 65 patients with recurrent high-grade glioma, the majority being recurrent glioblastoma (rGBM)." (PMID 38454126, 2024). "For example, in a glioblastoma model, bispecific CAR-T cells co-expressing IL13Rα2 and HER2 CAR molecules demonstrated stronger anti-tumor ability and reduced tumor escape than monospecific or HER2 and IL13Rα2 pooled CAR-T cells." (PMID 38622705, 2024). "The intraventricular injection of CAR-T cells directed against IL13Ra2 and HER2 has demonstrated efficacy in the treatment of glioblastoma and breast cancer brain metastases in preclinical models." (PMID 38892913, 2024). "In an orthotopic glioblastoma (GBM) model, TanCAR targeting HER2 and IL13Rα2 exhibited greater efficacy compared to bispecific CAR-T cells." (PMID 38622705, 2024). "To date, interleukin 13 receptor alpha 2 (IL13Ra2) and HER2 are the most frequently tested TAAs in clinical trials with published results regarding CAR-T cell therapy in glioblastoma." (PMID 36564524, 2023). "Additionally, CD4+ CAR T cells showed persistent tumor challenge and effective function, whereas CD8+ CAR T cells were exhausted immediately after expressing their effective function following stimulation with IL13Rα2+ glioblastoma (GBM) cells." (PMID 38328405, 2023). "In a CAR-based study, bispecific targeting of IL-13 receptor α2 (IL13Rα2) and human epidermal growth factor receptor 2 (HER2) was able to control glioblastoma for nearly a month whereas single-targeted CAR therapy was ineffective due to antigen escape." (PMID 36721153, 2023). "The source protein for peptide IVDPGYLGY was interleukin-13 receptor subunit alpha-2 (IL13Rα2), which has been reported to be overexpressed in 85% of DIPG cases and an effective CAR T-cell target for glioblastoma tumor regression." (PMID 37637064, 2023).
glioblastoma (continued). "Another trial is still assessing the effect of IL13Rα2 CAR T cells on medulloblastoma, glioblastoma, and ependymoma." (PMID 36721153, 2023). "In vivo testing of three antigen-targeted CAR T cells against glioblastomas (HER2, IL13Ra2, EphA2) led to successful antitumor responses against almost 100% of the tumour cells from patient-derived glioblastoma cell lines." (PMID 35205725, 2022). "In targeting glioblastoma cells, CAR-T cells modified with a targeted-quadruple-mutant of IL13 was combined with fluorescent therapeutic NPs and targeted to IL13Rα2 overexpressed glioblastoma cells." (PMID 35612318, 2022). "IL13Rα2, EGFRvIII, and HER2-targeted CAR-T cells have been evaluated in clinical trials in glioblastoma." (PMID 33753869, 2022). "A study found that T cells co‐expressing IL‐13Rα2‐CARs and HER2 showed improved tumor control in a human glioblastoma multiforme (GBM) orthotopic xenograft model." (PMID 34431224, 2021). "It has been demonstrated that chlorotoxin binds to most primary glioblastoma tumors, whereas antibodies to Her2, IL13Rα2, or EGFR binds to a small population of primary glioblastoma tumors." (PMID 34209505, 2021). "The same group described the first tandem CAR-T cells targeting HER2 and IL13Ra2, then trivalent CAR-T cells targeting HER2, IL13Rα2 and ephrin-A2, and showed better results in preclinical models of glioblastoma compared to monovalent CAR-T cells." (PMID 33874996, 2021). "To date, five valuable glioblastoma-specific cell surface antigens have been identified as targets for CAR T cells, such as EGFRvIII, HER2/neu, IL-13Rα2, B7-H3 and EphA27." (PMID 34707200, 2021). "CAR T cells can target glioblastoma-specific antigens, including interleukin-13 receptor subunit alpha-2 (IL-13Rα2), EGFR wt, and EGFRvIII, and are thus effective against glioblastoma in preclinical models." (PMID 33572835, 2021). "IL13Rα2 CAR T cells are also currently being clinically evaluated in combination with nivolumab and ipilimumab for recurrent and refractory glioblastoma (NCT04003649)." (PMID 34054867, 2021). "In vivo studies have shown that the use of a first-generation IL13Rα2 CAR-T cell construct was able to target and elicit an effector immune response against glioblastoma cells and GSCs." (PMID 34371744, 2021). "Chimeric antigen receptor (CAR)-T cells can specifically recognize tumor cells and target EGFRvIII, IL-13Rα2, and HER2 antigens expressed by glioblastoma." (PMID 33511267, 2020). "Interestingly, one of these studies showed a higher expression of IL13Rα2 on stem-like vs. differentiated glioma populations, indicating that IL13Rα2-directed immunotherapeutic approaches could be useful for eradicating therapeutically resistant glioblastoma stem cell (GSC) populations." (PMID 33101285, 2020). "CAR-T cells that double target IL-13Rα2 and HER2 also show good potential for improving the immune escape of glioblastoma." (PMID 33511267, 2020). "In glioblastoma, CAR-T against antigen IL13Rα2, human epidermal growth factor receptor 2 (HER2), and EGFRvIII have been developed." (PMID 31979318, 2020). "So far, CAR-T cells against IL-13Ra2, EGFRVIII, and HER2 have been tested in glioblastoma clinical treatment and have showed promising results." (PMID 31288857, 2019). "In glioblastoma studies, CAR T cells targeting IL-13Rα2 were modified to over-express transgenic IL-15 and demonstrated that IL-15 cytokine secretion was T cell activation dependent and resulted in improved CAR T cell persistence in vitro." (PMID 30863720, 2019). "The field of targeting through receptors progressed significantly with the discovery of an interleukin 13 receptor alpha 2 (IL-13RA2) as a tumor-associated receptor over-expressed in most patients with glioblastoma (GBM) but not in normal brain." (PMID 30366424, 2018). "In order to improve the antitumor activity, new IL13Rα2 CAR T cells coexpressing the CD137 were engineered, to improve the antitumor activity against glioblastoma." (PMID 30279357, 2018).